SKP2 (S-phase kinase associated protein 2)
Diseases named in the same sentence as SKP2 in open-access papers (continued):
Sharing a sentence is not in itself a finding about the gene and the disease.
tumor (continued). "Correspondingly, transfection with Skp2 siRNA could reduce Skp2 protein and induce the accumulation of p27 protein in MCF-7 cells, inhibited the MCF-7 cell proliferation in vitro and tumor growth in vivo." (PMID 34068643, 2021). "A selenonucleoside called LJ-2618 downregulates the expression of SKP2 by promoting its degradation and induces G2/M cell cycle arrest in prostate cancer cells and xenograft tumor in vivo." (PMID 34178666, 2021). "Positive immunostaining for SKP2 was detected in the nucleus, mainly on the superficial central compartment of the tumour rather than in the tumour margins." (PMID 34075107, 2021). "Interestingly, TCGA data analysis revealed that the CDK1, CDK2, CCNB2, and SKP2 genes were significantly upregulated, but the SKP1 gene was downregulated in tumor samples compared with normal samples." (PMID 31717435, 2019). "Remarkably, ectopic expression of Skp2 S256D, but not Skp2 S256A, in AMPK knockdown cells rescued the defect in tumor growth upon AMPK deficiency." (PMID 30413706, 2018). "MP-HX downregulated the expression of genes that could promote anti-apoptotic effect, cell cycle progression, tumor development and progression, which include BIRC5, CCNA2, CCNB1, CCNB2, CCNE2, CDK1/2/6, GINS2, HELLS, MCM2/10 PLK1, RRM2 and SKP2." (PMID 30042885, 2018). "Taken together, these observations suggested that SKP2 small-molecule inhibition, could in principle, elicits the highly penetrant Rb synthetic lethal effect seen in TNBC tumour cells with RNA interference reagents." (PMID 29915391, 2018). "Although not shown in PCa, SKP2 is a direct transcriptional target of MYC in tumor cells including leukemia and neuroblastoma." (PMID 29210989, 2017). "Overexpression of SKP2 alone did not lead to any tumor formation or histological alteration in mice up to 40 weeks post injection." (PMID 25537506, 2015). "Another E3 ligase, Skp2, could also mediate the ubiquitination of p57 by collaborating with CSN6 in the cytoplasm to regulate tumor progression." (PMID 26271467, 2015). "Our data indicate that overexpression of SKP2 per se is not sufficient to induce cellular transformation and tumor development in the liver, at least under our experimental setting." (PMID 25537506, 2015). "6-OAP treatment did not perturb Skp1 expression, but down-regulated NIPA and Skp2, and up-regulated Cyclin B1 and E-cadherin in tumor samples." (PMID 26474281, 2015). "Numb ablation by siRNA in vitro could inhibit tumor cell proliferation by downregulating CDK4 and SKP2 and upregulating p21 expression, and enhancing the apoptotic potential by upregulating BAK." (PMID 26165304, 2015). "The immunoreactivity of Skp2 was negative in normal tissue but increased in tumor tissues, where was stained as yellowish brown granules in the nuclei." (PMID 25015320, 2014). "In primary oral melanomas, 17.5% (range: 8.7% to 36.5%) of malignant cells expressed Skp2 in the nucleus, mainly on the superficial central compartment of the tumor rather than in the tumor margins." (PMID 23385514, 2013). "In agreement with the unaffected tumour size, expression of c-Myc, Skp2 and the proliferation marker Ki67 was comparable to littermate controls whereas the differentiation marker K10 was slightly reduced in K5-SOS Hdac2Δ/Δep tumours." (PMID 24240174, 2013). "Our data showed that Skp2 expression did not correlate with lymph node metastasis, but correlated with local tumor invasion." (PMID 22533738, 2012). "We did not observe a significant correlation between Skp2 levels and patient age (P = 0.083), lymph node status (P = 0.083), tumor size (P = 0.063), disease stage (P = 0.449), or Her2/neu expression (P = 0.088)." (PMID 18644126, 2008).
tumor (continued). "This suggests that high expression of Skp2 in a given tumor is an inherent feature of the tumor's biology rather than one that is acquired during progression of the disease." (PMID 18644126, 2008). "However, compared to large amounts of studies using a Skp2 knockout mouse model, direct in vivo evidence for human SKP2 on tumor initiation and prostatic microenvironment is still lacking." (PMID 41542047, 2026). "However, TRβ2 likely exerts additional, yet unidentified, roles in cell cycle regulation and survival, while TRβ1 may have broader tumor-suppressive functions beyond EMI1 and SKP2 regulation." (PMID 40605078, 2025). "Although this remains to be formally tested, a possible tumour suppressive role may arise through its relationship with SKP2, where EMI1 prevents the uncontrolled degradation of SKP2 by APC/CCDH1, thereby allowing SCFSKP2 to regulate Cyclin E1 abundance preventing its aberrant accumulation." (PMID 39358461, 2024). "Dioscin has been demonstrated to enhance the interaction between Skp2 and Cdh1, promoting Skp2 ubiquitination and degradation, and finally decreasing glucose consumption and lactate production in vitro, while treatment with Dioscin has also been shown to inhibit CRC tumor growth in vivo." (PMID 37089937, 2023). "The different performances between Skp2 inhibitor and Skp2-inhibiting compounds in SCLC cell lines and NSCLC cells lines, might provide a clue that Skp2 played more important roles in SCLC than in NSCLC cells from the point of tumor pathological mechanisms." (PMID 37089937, 2023). "Besides the newly-identified EGFR, the tumor growth and metastasis suppression effects of FBXW2 in PCa might be induced through other potential substrates of FBXW2, like SKP2." (PMID 35499593, 2022). "CD34 expression was markedly reduced in AMPK knockdown tumor, which could be rescued by Skp2 S256D, but not Skp2 S256A." (PMID 30413706, 2018). "Noticeably, the tumor suppressor proteins whose levels have been shown to be downregulated by SKP2-dependent degradation in various tumor types, including p27, p57, Dusp1, and Rassf1A were not decreased in liver lesions from SKP2/N-RasV12 and SKP2/myr-AKT1 mice." (PMID 25537506, 2015). "In addition, overexpression of SKP2 did not modify the ratio of tumor types developed in SKP2/myr-AKT1 mice when compared with myr-AKT1 mice." (PMID 25537506, 2015). "Besides gain of the region covering the SKP2 gene, we found a significant increase in expression between normal cervical epithelial cells, tumour cells without amplification and tumour cells with amplification." (PMID 17311676, 2007). "Our results here may unveil the puzzle that loss of PCBP1 destabilizes p27 mRNA at the first step to lead to low p27 expression, irrespective of Skp2 levels and the posttranslational regulation via other manners, since Skp2 expression is rarely seen to be upregulated in the detected tumor samples." (PMID 30086790, 2018). "Unlike tumor suppressive E3 ligase such as FBW7 and FBXO4, or oncogenic E3 ligase such as SKP2, β-TRCP (β-TRCP1 and β-TRCP2) displays context-dependent (tumor type or cellular context) functions in tumorigenesis." (PMID 29497989, 2018). "We found that β-TrCP1 and SKP2 mRNA levels were always higher (e and data not shown), whereas FBXW2 mRNA levels were lower in tumours than that in normal tissues (and data now shown)." (PMID 28090088, 2017). "In this tumor type, disruption of the negative control operated by kinesin family member 14 (KIF14) on SKP2 seems to be responsible for SKP2 unconstrained activity." (PMID 25537506, 2015). "In subgroup analysis, a correlation between Skp2 and DSS was seen in patients with malignancy grade 1 or 2 (P = 0.027), tumor size >5 cm (P = 0.018), no radiotherapy given (P = 0.029) and no chemotherapy given (P = 0.017)." (PMID 23071715, 2012).
tumor (continued). "Furthermore, we have previously shown in mice that SKP2 overexpression alone is not sufficient to induce malignant liver transformation, but it cooperates with oncogenic NRAS (NRASV12) to induce tumor development." (PMID 39064589, 2024). "For example, overexpression of MEX3B in tumors can reduce the lethality of tumor-infiltrating lymphocytes, thereby mediating tumor immunotherapy resistance; NONO promotes cancer proliferation by regulating SKP2 and E2F8, significantly affecting patient prognosis." (PMID 35647031, 2022).
infection (11 papers, 2011 to 2026). The state of being infected such as from the introduction of a foreign agent such as serum, vaccine, antigenic substance or organism. "aureus infection, we demonstrate increased SKP2 abundance through acetylation-induced stabilization and translocation into the cytoplasm." (PMID 41834993, 2026). "Infection of VeroB4 cells with MERS-CoV facilitated increased phosphorylation of SKP2 at S72, with a concomitant decrease of cellular levels of BECN1 and enhanced K48-polyubiquitinylation of BECN1." (PMID 31852899, 2019). "Western blot analysis of total protein extracts revealed that although cyclin-D1 levels were unaffected, both MAD2 and Skp2 levels were diminished in alveolar macrophages upon in vivo infection." (PMID 22396644, 2012). "mTOR inhibitor, PP242, treatment directly inhibits CK1α kinase activity and disrupts the LT interaction with both β-TrCP and Skp2, which explains a greater inhibition effect on LT destruction complex, resulting in enhanced MCPyV replication and infection shown in the previous studies." (PMID 38940554, 2024). "In addition to rejuvenating EPC senescence phenotypes, angiogenic activity was evaluated by injecting senescent EPCs with adenoviral-mediated Skp2 infection into the ischemic hind limbs of nude mice." (PMID 32313103, 2020). "SKP2-targeting compounds also may have potential against other infections and other clinical conditions that are influenced by autophagy induction." (PMID 31852899, 2019). "Interestingly, when analysing the behaviour of tissue macrophages upon in vivo infection by C. neoformans, only reduction of Skp2 levels were observed in alveolar macrophages." (PMID 22396644, 2012). "CUL1 and CCNE1, two S phase target genes, whose mRNA levels were upregulated at various time points after DTMUV infection, while the mRNA levels of RBX1, SKP2 and CCNE2 were decreased at all the time points, moreover, CCNE2 was time-dependently downregulated." (PMID 32897243, 2020). "Infection of PFC and NFC with Skp2 siRNA resulted in significant inhibition of cell proliferation and metabolic activity in vitro." (PMID 21270971, 2011). "Whereas infection of NRVMs with AdXBP1s resulted in increases in SKP2 mRNA, SKP2 knockdown using SKP2-specific siRNA (siSKP2) did not relieve Xbp1s-dependent FoxO1 protein degradation." (PMID 33727534, 2021). "Autophagy is the suicidal mechanism that an infected cell adopts to protect adjacent cells from further infection., When SARS-CoV-2 infects a cell, the virus will forestall the autophagy mechanism by releasing SKP2 protein that can inhibit the cell’s Beclin-1 production." (PMID 34961070, 2021). "As for WT (KN99α) C. neoformans, the acapsular strain (cap59D), which also induced cell cycle alteration and aneuploidy, led upon infection to decreased levels of MAD2, cyclin-D1 and Skp2, in contrast to serotype D strain (JEC21), which had no impact on the levels of these proteins as expected." (PMID 22396644, 2012).
prostate (6 papers, 2012 to 2026). "To explore the role of SKP2 on epigenetics and the relevance on PCa progression in vivo, we wished to investigate whether Skp2 deficiency suppresses prostate tumorigenesis through affecting the functional coupling of JARID1B and H3K4me3 in mouse models." (PMID 25596733, 2015). "All evidence suggests that SKP2 functions as a key oncogene during prostate carcinogenesis and progression." (PMID 41542047, 2026). "We therefore have established a more pathophysiologically relevant prostate carcinogenesis model by knocking-in of human SKP2 gene into a locus that is regulated by the endogenous probasin promoter using the CRISPR/Cas9 method." (PMID 41542047, 2026). "Our results suggest SKP2 overexpression is an early event in prostate carcinogenesis." (PMID 41542047, 2026). "Therefore, there is an unmet need to develop a hSKP2-KI mouse model for further understanding the oncogenic functions of SKP2 in prostate carcinogenesis and to provide a novel tool for developing novel SKP2 inhibitors." (PMID 41542047, 2026). "Additionally, KDM5B protein stability was regulated by S-phase kinase associated protein-2 (SKP2), which elevated H3K4me3 level to facilitate prostate carcinogenesis by promoting ubiquitination-dependent degradation of KDM5B." (PMID 27974677, 2017).
adenocarcinoma (4 papers, 2016 to 2026). A common cancer characterized by the presence of malignant glandular cells. "The adenocarcinomas that are heavily infiltrated with Tregs show a higher expression of SKP2." (PMID 34414959, 2021).
hematological malignancies (3 papers, 2022 to 2024). "Concerning hematological malignancies, SKP2 being a crucial regulator of the cell cycle, plays a multifaceted role." (PMID 38559562, 2024). "Clinically, the elevated expression of Skp2 is recognized as a poor prognostic marker in many solid tumor cancers and hematological malignancies." (PMID 38559562, 2024). "For example, dysregulation of Skp2 expression plays a carcinogenic role in hematological malignancies." (PMID 35845132, 2022). "It is interesting to note that SKP2 overexpression was observed in multiple solid tumors as well as hematological malignancies." (PMID 35741710, 2022). "Similarly, an inverse correlation between Skp2 and p27 gene expression is also frequently found in hematological malignancies." (PMID 38559562, 2024). "In the current review, we discussed the novel role of SKP2 in different hematological malignancies." (PMID 38559562, 2024). "In addition, SKP2 overexpression was observed in several human malignancies, such as breast cancer, non-small-cell lung cancer, pancreatic cancer, gastric cancer, prostate cancer, melanoma, and hematological malignancies." (PMID 35741710, 2022). "To improve the predictive value and therapeutic specificity of the Skp2 gene in solid and hematological malignancies, we analyzed the TCGA data (data not shown)." (PMID 38559562, 2024).
vasculopathy (2 papers, 2020 to 2023). "We investigated whether Skp2 plays a role in the regulation of endothelial progenitor cell (EPC) senescence, which is closely associated with aging-related vasculopathy." (PMID 32313103, 2020). "The slowdown of cell cycle relates to cellular senescence closely, and the Skp2 inhibition induces the senescence of endothelial progenitor cell (EPC), and inhibits angiogenic senescence, leading to aging-related vasculopathy, which finally affects atherosclerosis related disease or vascular event." (PMID 37089937, 2023).
SKP2 also shares sentences with these, for which no sentence is quoted: ischemia (3 papers); lung squamous cell carcinoma (3); prostate intraepithelial neoplasia (3); chronic lymphocytic leukemia (2); diabetes (2); Diabetic Nephropathy (2); dysplastic nevi (2); fatty liver (2); injury (2); Insulin resistance (2); mesothelioma (2); metastatic prostate carcinoma (2); ovarian adenocarcinoma (2); systemic lupus erythematosus (2); T-cell acute lymphoblastic leukemia (2); Urinary Bladder Urothelial Carcinoma (2); acute lung injury (1); acute promyelocytic leukemia (1); adrenal tumor (1); adrenocortical carcinoma (1); benign breast diseases (1); biliary tract cancer (1); bone tumors (1); cervical intraepithelial neoplasia (1); cervical squamous cell carcinoma (1); Chronic colitis (1); clear cell renal cell carcinoma (1); co-infection (1); cutaneous T-cell lymphoma (1); cystic kidney disease (1).
A further 40 diseases each share a sentence with SKP2 in 1 paper.